CAT (catalase)
Diseases named in the same sentence as CAT in open-access papers (continued):
Sharing a sentence is not in itself a finding about the gene and the disease.
ischemic stroke (19 papers, 2019 to 2025). A stroke disorder caused by obstruction of blood flow to the brain, due to thrombotic (local blood clot formation) or embolic (due to a blood clot or other material traveling from another site) event. "We did not include direct markers of oxidative stress (e.g., malondialdehyde, 8-iso-PGF2α, glutathione, superoxide dismutase, catalase), which limits our ability to capture the redox imbalance associated with ischemic stroke." (PMID 41300462, 2025). "This study aimed to investigate the association between antioxidant markers (SOD, GSH, NO, and Catalase) and ischemic stroke severity and recovery outcomes in a cohort of 364 patients." (PMID 40837372, 2025). "In contrast, our study specifically investigated the relationship between antioxidant markers – SOD, GSH, catalase, and NO – with ischemic stroke severity and recovery outcomes in a larger cohort over 6 months." (PMID 40837372, 2025). "This randomised controlled trial aimed to investigate the relationship between antioxidant markers (Superoxide Dismutase [SOD], Glutathione [GSH], Catalase, and Nitric Oxide [NO]) and the severity of ischemic stroke in affected individuals." (PMID 40837372, 2025). "This study seeks to address the gap in knowledge by exploring the relationship between antioxidant markers – specifically SOD, GSH, Catalase, and NO – and ischemic stroke severity, as well as the potential for recovery in human subjects." (PMID 40837372, 2025). "To overcome these barriers, we designed an ischemia-homing bioengineered nano-scavenger by camouflaging a catalase (CAT)-loaded self-assembled tannic acid (TA) nanoparticle with a M2-type microglia membrane (TPC@M2 NPs) for ischemic stroke treatment." (PMID 36045405, 2022). "Further studies are needed to determine whether catalase plays a more time-dependent or localised role in ischemic stroke and whether other enzymatic interactions influence its function." (PMID 40837372, 2025). "One possible explanation is that while catalase is essential for detoxifying hydrogen peroxide, its role may be more limited in the broader context of ischemic stroke pathology." (PMID 40837372, 2025). "Inhibiting catalase or dynamin-related protein 1 (Drp1), a protein needed for peroxisomal fission, led to increased neuronal susceptibility to death from oxygen-glucose deprivation (OGD), a cellular model of ischemic stroke." (PMID 32210766, 2020). "These may involve the activation of Akt and eNOS, with the subsequent stimulation of antioxidant defenses (e.g., glutathione, catalase, superoxide dismutase) and reduction of reactive oxygen species (ROS) formation, as observed in ischemic stroke." (PMID 32143329, 2020). "However, activation of the CAT inhibitor, 3-amino-1, 2, 4- triazole, prior to ischemic stroke, abolished the beneficial effects of HBOT, like spinal cord resilience to oxidative stress decreased significantly." (PMID 32899709, 2020). "A more positive link has been found between peroxisomes and ischemic stroke; peroxisomal volume in in vitro and in vivo models of ischemia increased after injury, leading to an increased number of peroxisomes, as well as increased expression of peroxisomal catalase." (PMID 32210766, 2020). "In ischemic stroke, the evaluation of antioxidant enzymes was extensively carried out: superoxide dismutase (SOD), glutathione peroxidase (GPx), and catalase (CAT)." (PMID 37047362, 2023). "Animal model studies showed that ischemic stroke is generally followed by enzymatic antioxidant defense weakening, with dramatic falls in SOD, GPx, and CAT activities." (PMID 37047362, 2023). "Animal studies suggest that pretreatment of rats with resveratrol before ischemic stroke significantly enhances Zn level so as to increase the antioxidant enzyme activity of SOD and CAT in the ischemic brain." (PMID 35204278, 2022).
ischemic stroke (continued). "For instance, electroacupuncture (EA) at GV20 (Baihui) and GV24 (Shenting) has been shown to enhance cerebral blood flow and mitigate oxidative damage in ischemic stroke models, likely through upregulation of antioxidant enzymes (e.g., SOD, CAT) and suppression of lipid peroxidation." (PMID 40546257, 2025). "In the current study, AESF treatment upregulated the activity of CAT and the levels of SOD in CI/RI rats, which indicated that the protective effects of safflower on ischemic stroke might be conferred through alleviating oxidative stress." (PMID 39776584, 2024).
leukemia (19 papers, 2010 to 2025). A malignant (clonal) hematologic disorder, involving hematopoietic stem cells and characterized by the presence of primitive or atypical myeloid or lymphoid cells in the bone marrow and the blood. "To investigate mechanisms underlying differential catalase expression in leukemia, among the SNPs in the human CAT gene we focused on the rs1001179 SNP in the CAT promoter since it has been associated with altered CAT expression in normal peripheral blood cells." (PMID 36112236, 2022). "To assess the role of these enzymes in the methylation of CAT promoter in leukemia cells, first we characterized DNMT1, DNMT3A, TET1-3 mRNA expression levels in CLL and HD B cells." (PMID 36112236, 2022). "In conclusion, our data advance the knowledge of the role of genetic and epigenetic mechanisms controlling CAT expression in leukemia." (PMID 36112236, 2022). "This dichotomous expression of CAT in CLL subsets with divergent clinical behaviors highlights the importance to decipher the molecular mechanisms regulating CAT expression in leukemia cells." (PMID 36112236, 2022). "Multidrug-resistant leukemia cells HL-60 with high expression of catalase protect from the cytotoxic effects of hydrogen peroxide." (PMID 32318339, 2020). "For example, the upregulation of antioxidant enzyme catalase resulted in a 10-fold resistance to H2O2 or tert-butyl hydroperoxide in HL-60/AR leukemia cells." (PMID 32047536, 2020). "A significant reduction in the activity of CAT has been observed in many types of cancer: head and neck, lungs, gastrointestinal tract, breasts, kidney, or leukemia." (PMID 31781331, 2019). "We next evaluated the contribution of STAT5 in the regulation of catalase and Glrx1 protein expression and found that RNA interference-mediated knockdown of STAT5 in Bcr-Abl+ leukemia cells increased the expression of catalase and Glrx1 (2 to 3 fold)." (PMID 27566554, 2017). "Catalase was shown not only to reduce ROS levels but also, to induce quiescence in Bcr-Abl-positive leukemia cells." (PMID 27566554, 2017). "However, further investigations are required to address the impact of genetic and epigenetic mechanisms of catalase regulation as well as their interactions on leukemia progression and resistance." (PMID 36112236, 2022). "Notably, NAD depletion was still found to occur in APO866-treated leukemia cells despite the presence of exogenous catalase, indicating that the contribution of ROS/RNS productions to APO866-induced cell death occurs downstream of NAD depletion." (PMID 31803365, 2019). "Besides this activity, this present study and previous works have shown that ATO decreased catalase expression in solid tumors and leukemia." (PMID 29467594, 2018). "The contribution of catalase in the regulation of quiescence is also underscored by data obtained from the co-culture experiments aiming to mimic the bone marrow microenvironment of leukemia cells." (PMID 27566554, 2017). "Furthermore, reduction of STAT5 phosphorylation and upregulation of catalase and Glrx1 were also evidenced in leukemia cells co-cultured with bone marrow stromal cells to mimic a leukemic niche." (PMID 27566554, 2017). "Also the catalase expression was modulated by the acetylation of histone H4 in leukemia cells, indicating that the regulation of catalase expression is a complex and elusive mechanism involving at least three pathways." (PMID 24057278, 2013). "Thus, this leukemia-specific methylation pattern suggests that the co-methylation process between nearby CpG sites may be dysregulated in the CAT promoter of CLL cells." (PMID 36112236, 2022). "Indeed, both overexpression and suppression of catalase have been observed in leukemia cells." (PMID 25115845, 2014). "To investigate the ability of CAT rs1001179 SNP to stratify CLL patients, we analyzed the relationship between the SNP genotypes and leukemia progression." (PMID 39540258, 2024).
leukemia (continued). "Consistent with the present study, EANT enhanced the mRNA expressions of NFE2L2, CAT, TXN, HMOX1, and NQO1 genes in leukemia cells in response to EANT-induced oxidative stress." (PMID 34573042, 2021). "Our results suggest that stromal-derived signals induce quiescence of Bcr-Abl+ leukemia cells in part, through a STAT5/catalase dependent pathway." (PMID 27566554, 2017). "Altered levels of catalase, another important scavenger of H2O2 mainly located in peroxisomes, have been found in leukemia although with conflicting roles depending on the type of leukemia in which it is expressed and the treatment status." (PMID 33671113, 2021). "To confirm that cell death protection by ROS/RNS scavengers indeed reflects the suppression of oxidative/nitrosative stress, we examined ROS production in APO866-treated leukemia cells in presence/or absence of catalase." (PMID 31803365, 2019). "Then, we assessed ATP cell content in APO866-treated leukemia cells in presence or absence of catalase." (PMID 31803365, 2019).
type 1 diabetes (19 papers, 2012 to 2025). "It has also been reported that low blood CAT levels cause oxidative stress conditions, which in turn promote type I diabetes." (PMID 37772794, 2023). "Children with type 1 diabetes and their siblings also had higher catalase activity (CAT) and lower total antioxidant status (TAS)." (PMID 36290631, 2022). "Their study demonstrated a protective role of the −262T CAT allele and the “+” GSTM1 allele against the rapid development of oxidative stress in type 1 diabetes related to increased levels of CAT, GSH, and GST in patients with these alleles." (PMID 34836227, 2021). "In the present study, we found that the SOD, GPX, and CAT activity levels were upregulated after 10 weeks of CS administration, indicating that CS could inhibit oxidative stress in type 1 diabetic rats; this may be one of important reasons why CS could prevent bone loss in type 1 diabetic rats." (PMID 34777254, 2021). "The blood catalase level was found to be low in CC individuals which results in oxidative stress conditions, thereby promoting type 1 diabetes." (PMID 31827713, 2019). "Additional research by others has confirmed that administration of zinc reversed the reduction of multiple antioxidants including catalase, superoxide dismutase, glutathione-S-transferase, glutathione peroxidase, and glutathione reductase in the type 1 diabetic liver." (PMID 34307690, 2021). "The STZ-induced type 1 diabetic rats showed a significant decrease in GSH (4.31 ± 0.150, p ≤ 0.001), SOD (29 ± 0.040, p ≤ 0.01), CAT (0.05 ± 0.006, p ≤ 0.05) and C-peptide levels (0.5 ± 0.220, p ≤ 0.0001) when compared to the normal control group." (PMID 30285704, 2018). "PDK1 is a kinase that inactivates pyruvate dehydrogenase, and Artemether treatment was found to reduce the level of mitochondrial protein PDK1, reverse the low expression of catalase, SOD2, and other antioxidant enzymes, and alleviate the redox imbalance in type 1 diabetes (T1D) DKD mice." (PMID 36712696, 2022). "MAK shows antidiabetic effects by relieving oxidative stress in STZ-induced type 1 diabetic animals; MAK ameliorates lipid peroxidation and dysfunction of antioxidative enzymes (superoxide dismutase, catalase, and glutathione peroxidase) in the brain, liver, and kidney in diabetic animals." (PMID 25945116, 2015).
dementia (18 papers, 2015 to 2025). Loss of intellectual abilities interfering with an individual's social and occupational functions. "Third, a few potential outcome predictors other than sex, such as lower baseline behavioral and psychotic symptoms of dementia, higher BMI, younger age, and higher baseline catalase levels, have been reported to be associated with greater improvement in ADAS-cog in some of the included studies." (PMID 39315325, 2024). "We observed an association of CAT rs1001179 with MMSE in all patients with dementia." (PMID 36829875, 2023). "Here, the levels of SOD2 and catalase are changed at 12 months of age in the SAMP8 model of early dementia and were changed to that of a young SAMP8 mouse." (PMID 40811673, 2025). "Observed associations of polymorphisms in CAT, GSTP1, NFE2L2 and KEAP1 with dementia support the importance of antioxidative mechanisms in AD." (PMID 36829875, 2023). "Superoxide dismutase, catalase and glutathione peroxidase activity in saliva in patients with dementia was decreased compared to the control group." (PMID 33671562, 2021). "The salivary uric acid levels, catalase and peroxidase activity were significantly lower in dementia patients compared to the controls." (PMID 33671562, 2021). "As we expected, the scopolamine dementia group significantly increased lipids peroxidation and decreased catalase activity and SOD activity." (PMID 31781268, 2019). "Moreover, increased activity of both catalase and GSTs has been found in CSF and blood samples of patients with different dementia types." (PMID 36829875, 2023). "Among antioxidative genes, CAT, GSTP1, NOS1, NFE2L2, and KEAP1 were associated with dementia or AD." (PMID 36829875, 2023). "Results representing the effects of different treatments on catalase activity show that Z. mucronata-treated groups increased the activity of this antioxidant significantly ((F5, 29) = 5.907; p < 0.0011) when compared with the dementia group." (PMID 31781268, 2019). "In an aluminum chloride-induced dementia in rats, caffeic acid (100 mg/kg, p.o.)improved cognitive ability and normalized acetylcholine esterase activity, nitrite and glutathione levels, as well as the protein expression of catalase (CAT) and glutathione-S-transferase (GST) in the brain." (PMID 36614030, 2022). "The antioxidant properties of myrtenal in the experimental model of dementia were evaluated by determining the levels of LPO products, tGSH content, and activity of some main antioxidant enzymes in the brain—SOD, CAT, and GPx." (PMID 35204256, 2022). "The activity of SP and CAT as well as the level of GSH and TAS were significantly lower in NWS of severe dementia patients compared to those with mild and moderate dementia (p < 0.001 in all groups)." (PMID 31212834, 2019). "In SWS, the activity of SP and CAT, and the level of GSH and TAS were considerably lower in patients with severe dementia compared to those with mild and moderate dementia (p < 0.001 in all groups)." (PMID 31212834, 2019). "In this study, both the activity of antioxidant enzymes (Px and CAT) as well as UA and TAC concentrations were significantly lower in NWS and SWS of patients with dementia." (PMID 29053628, 2017). "After 8 and 14 days pretreatment of the scopolamine-induced dementia rat with the hydroalcoholic extract of E. coccinae (200 and 400 mg.kg), there was a significant improvement of the levels of SOD, CAT and GSH whereas MDA level was decreased significantly." (PMID 26400617, 2015). "The results of antioxidant study showed decreased levels of SOD, CAT, and GSH in the scopolamine-induced dementia rat compared to normal rats." (PMID 26400617, 2015). "In particular, studies have shown that it increases the activity of endogenous antioxidant systems such as CAT, SOD, and GPx in the liver and pancreas of diabetic rats, as well as in the brain tissue of mice with dementia, while reducing levels of oxidative‐inflammatory markers like TNF‐α and MDA." (PMID 40025781, 2025).
dementia (continued). "001, respectively) and CAT (p < 0.001 in both groups), the level of GSH (p < 0.001 in both groups) and TAS (p < 0.001 in both groups) was significantly lower in patients with mild and moderate as well as severe dementia compared to the control group." (PMID 31212834, 2019). "Therefore, it is plausible that the anti-dementia effects of SSY in UCMS-exposed mice are mediated by its ability to counteract UCMS-induced reductions in SOD and CAT activities and lipid oxidation in the FC and HP, suggesting a strong antioxidant and neuroprotective effect of SSY formula." (PMID 40508195, 2025). "Moreover, some of the compounds (CAT, GSH, TAS, and Px) were also decreased in stimulated and unstimulated saliva from individuals with severe dementia more than in those with mild to moderate dementia." (PMID 32059422, 2020). "The activity of catalase, salivary peroxidase, level of total antioxidant capacity, and reduced glutathione were significantly lower in both the stimulated and nonstimulated saliva samples from patients with dementia than in the control groups." (PMID 32059422, 2020). "The activity of CAT (p < 0.001 in both groups) as well as the level of GSH (p < 0.001 in both groups) and TAS (p < 0.001 in both groups) were significantly lower in NWS in patients with mild and moderate as well as severe dementia compared to the control group." (PMID 31212834, 2019).